AHSG (alpha 2-HS glycoprotein)
Description:
Promotes endocytosis, possesses opsonic properties and influences the mineral phase of bone. Shows affinity for calcium and barium ions.
Synonyms: FETUA; A2HS; HSGA; AHS; APMR1
Tractability: Antibody: its Gene Ontology location is reachable by antibodies, with high confidence; UniProt places it where antibodies can reach, with medium confidence; UniProt predicts a signal peptide or a membrane-spanning region. PROTAC: ubiquitination databases record sites on it; its protein half-life has been measured.
Gene: Protein-coding gene on chromosome 3 (186,612,776 to 186,621,318, forward strand). Ensembl gene ENSG00000145192.
Subcellular location: Secreted
Subcellular location (Human Protein Atlas): Golgi apparatus; Predicted to be secreted
Pathways (Reactome):
Metabolism of proteins: Post-translational protein phosphorylation; Regulation of Insulin-like Growth Factor (IGF) transport and uptake by Insulin-like Growth Factor Binding Proteins (IGFBPs)
Hemostasis: Platelet degranulation
Immune System: Neutrophil degranulation
Gene Ontology:
Molecular function: protein binding; endopeptidase inhibitor activity; kinase inhibitor activity; cysteine-type endopeptidase inhibitor activity
Biological process: acute-phase response; positive regulation of phagocytosis; regulation of inflammatory response; negative regulation of bone mineralization; negative regulation of insulin receptor signaling pathway; pinocytosis; regulation of bone mineralization; skeletal system development
Cellular component: blood microparticle; extracellular exosome; extracellular region; Golgi apparatus; endoplasmic reticulum lumen; extracellular matrix; platelet alpha granule lumen; secretory granule lumen
Genetic constraint (gnomAD): Loss-of-function variants: 20 observed, 27.89 expected, observed/expected ratio (o/e) 0.72, 90% interval 0.5 to 1.04. The upper end of that interval is the gene's LOEUF score, 1.04, which puts it in group 4 of 6, group 1 being the genes least tolerant of losing a copy. Missense variants: 444 observed, 452.23 expected, observed/expected ratio (o/e) 0.98, 90% interval 0.91 to 1.06. Synonymous variants: 153 observed, 188.72 expected, observed/expected ratio (o/e) 0.81, 90% interval 0.71 to 0.93.
Homologues: Orthologues: chimpanzee AHSG (98% identical), macaque AHSG (85% identical), dog AHSG (69% identical), guinea pig AHSG (61% identical), rabbit AHSG (60% identical), mouse Ahsg (58% identical), pig AHSG (58% identical), rat Ahsg (54% identical), tropical clawed frog ahsg (35% identical), zebrafish ahsg2 (29% identical). Paralogues in human: FETUB (21% identical), HRG (21% identical), KNG1 (16% identical).
Diseases named in the same sentence as AHSG in open-access papers:
AHSG is named in the same sentence as 289 diseases in open-access papers, as found by Europe PMC text mining. Sharing a sentence is not in itself a finding about the gene and the disease. The quoted sentences say what the papers report.
Insulin resistance (160 papers, 2008 to 2025). Increased resistance towards insulin, that is, diminished effectiveness of insulin in reducing blood glucose levels. "α-2-HS glycoprotein (AHSG), also known as fetuin-A, is closely linked to metabolic diseases, e.g., insulin resistance and diabetes mellitus." (PMID 40625923, 2025). "AHSG is a glycoprotein that inhibits insulin receptor tyrosine kinase and is associated with insulin resistance, diabetes type 2, and metabolic syndrome." (PMID 36214631, 2022). "Then, in the past two decades, the alpha-2-HS-glycoprotein was linked to insulin resistance, obesity, and cardiovascular diseases." (PMID 34945026, 2021). "AHSG has been also recognized as antagonist of insulin receptor tyrosine kinase activity and is implicated in insulin resistance development." (PMID 28855568, 2017). "It improves insulin resistance and hepatic steatosis by attenuating α-2-HS-glycoprotein (AHSG), suggesting its involvement in the pathogenetic mechanisms of diabetes and NAFLD." (PMID 40625923, 2025). "High circulating levels of alpha-2-HS-glycoprotein were also found in the serum of humans with depressive episodes and anxiety within the context of insulin resistance." (PMID 37235602, 2023). "Fetuin-A, the protein product of AHSG gene, is a hepatokine and is known to be associated with insulin resistance and type 2 diabetes." (PMID 35359973, 2022). "An independent risk factor for type 2 diabetes is the plasma levels of AHSG, which is an insulin receptor inhibitor secreted by the liver and, along with FETUB, thought to be an important factor in insulin resistance in obesity." (PMID 35745003, 2022). "Recently, sex hormone binding globulin (SHBG) and fetuin-A (AHSG) have been shown to play an important regulatory role in insulin resistance, and can thus represent promising targets for future therapeutics." (PMID 33536069, 2021). "Fetuin-A is a glycoprotein mainly expressed by the liver, and its coding gene is AHSG, which is found on chromosome 3q27, this locus being typical of obesity, insulin resistance, DM2, metabolic syndrome, and nonalcoholic fatty liver disease (NAFLD)." (PMID 33807959, 2021). "AHSG is another glycoprotein that exhibits peripheral insulin resistance via protease regulation." (PMID 32933222, 2020). "As well, the serum levels of AHSG are positively correlated with steatosis and insulin resistance." (PMID 30395577, 2018). "Another support for our model comes from a recently reported functional study in which the alpha-2-HS-glycoprotein (ASHG) has been identified as an adaptor protein that links saturated fatty acids to toll-like receptor 4 thus stimulating inflammatory pathways leading to insulin resistance." (PMID 23308243, 2013). "Melatonin improves insulin resistance and hepatic steatosis by downregulating AHSG and reducing endoplasmic reticulum stress, highlighting the therapeutic potential of targeting fetuin-A in NAFLD." (PMID 40625923, 2025). "Short-term high-fat diet-induced steatosis, liver macrophage activation, and hepatic insulin resistance together with a significantly increased expression of liver AHSG (α2-HS glycoprotein/fetuin-A) mRNA and serum fetuin-A concentration." (PMID 36355106, 2022).
diabetes (92 papers, 2010 to 2025). "Other studies have also been devoted to assessing the role of AHSG polymorphisms in the risk of developing diabetes." (PMID 41155157, 2025). "Other studies have shown that a single nucleotide polymorphism (SNP) of AHSG gene was associated with the prevalence of type 2 diabetes mellitus, and circulating fetuin-A concentration was negatively correlated with insulin secretion." (PMID 32134969, 2020). "We suggest that the alpha-2-HS-glycoprotein could be an aqueous-specific marker of cataract risk, which is highly associated with diabetes." (PMID 34945026, 2021). "However, our results are the first to report that human aqueous levels of the alpha-2-HS-glycoprotein are associated with diabetes risk factors for cataract formation." (PMID 34945026, 2021). "Among the identified proteins, alpha-2-HS-glycoprotein is reportedly associated with IR and diabetes; fibrinogen alpha chain with chronic inflammation, lipid metabolism, and diabetic complications; and fibrinogen gamma chain and secreted phosphoprotein 24 with lipid metabolism and obesity." (PMID 34646426, 2021). "The search strategy used key terms and Boolean combinations such as "fetuin-A", "AHSG gene", "adiponectin", "ADIPOQ polymorphism", "genetic variants", and "type 2 diabetes mellitus"." (PMID 41341358, 2025). "On the other hand, FETUA (AHSG, alpha 2-HS glycoprotein), a plasma glycoprotein predominantly synthesized in the liver, is increased in type 2 diabetes mellitus, metabolic syndrome, and nonalcoholic fatty liver disorder (NAFLD)." (PMID 34867397, 2021). "All these previous studies reported the correlation of alpha-2-HS-glycoprotein levels in urine or serum with diabetes." (PMID 34945026, 2021). "More studies are also required to analyze the alpha-2-HS-glycoprotein levels in AH of non-diabetic cataract patients, along with further serum and AH comparison analyses of cataract patients with diabetes." (PMID 34945026, 2021).
Obesity (92 papers, 2010 to 2025). Accumulation of substantial excess body fat. "During obesity and related complications such as type 2 diabetes, metabolic syndrome, and non-alcoholic fatty liver disease, the circulating level of Alpha-2-HS-glycoprotein is significantly increased." (PMID 40709343, 2025). "A previous study detected significant upregulation of AHSG expression in diet-induced obesity rat models." (PMID 37889672, 2023). "Genetic influences also impact fetuin-A concentrations and functions; AHSG single-nucleotide polymorphism was found to be susceptible for obesity and early-onset co-morbidities." (PMID 34575030, 2021). "aHSG/fetuin-A is an insulin receptor inhibitor that is produced in the liver and an important link between obesity and insulin resistance." (PMID 33833309, 2021). "The positive association between AHSG expression and the risk of developing CRC stems from the effect of AHSG on obesity and insulin resistance." (PMID 34907282, 2021). "Circulating levels of AHSG, ANGPTL4 and LECT2 were previously demonstrated to correlate with obesity, BMI or waist circumference in humans." (PMID 35409319, 2022). "Although the potential therapeutic relevance of modulating the expression/activity of AHSG, ANGPTL4, LECT2 and FGF21 for treating obesity, IR and liver metabolic disorders is still unclear, targeting these hepatokines appears to be a promising strategy in addition to other currently used therapies." (PMID 35409319, 2022).
metabolic syndrome (71 papers, 2008 to 2025). A cluster of metabolic risk factors for CARDIOVASCULAR DISEASES and TYPE 2 DIABETES MELLITUS. "The secreted liver protein fetuin-A (AHSG) is up-regulated in hepatic steatosis and the metabolic syndrome." (PMID 18335040, 2008).
chronic kidney disease (53 papers, 2010 to 2026). Impairment of the renal function secondary to chronic kidney damage persisting for three or more months. "In turn, another study examined the association of selected SNPs in AHSG—rs4917 and rs4918—with serum fetuin-A levels, coronary artery calcification (CAC), and mortality in patients after kidney transplantation, and in patients with chronic kidney disease (CKD)." (PMID 41155157, 2025).
Hepatic steatosis (46 papers, 2008 to 2025). Steatosis is a term used to denote lipid accumulation within hepatocytes. "Although our analysis identified AHSG (also known as fetuin A) as a thermogenic signal to boost lipid breakdown in adipose tissue, elevated fetuin A levels in humans are a significant risk factor for metabolism-associated fatty liver disease in humans." (PMID 40498837, 2025). "Fetuin-A (α2-HS glycoprotein, AHSG) is a glycoprotein produced primarily in the liver and secreted into circulation in high concentrations in humans with fatty liver disease; it binds the insulin receptor and inhibits hepatic and muscle insulin signaling resulting in insulin resistance." (PMID 30123261, 2018).
non-alcoholic fatty liver disease (29 papers, 2014 to 2025). "DPP4 and AHSG were both suggested as biomarkers for non-alcoholic fatty liver disease." (PMID 30188931, 2018).
COVID-19 (17 papers, 2021 to 2024). A disease caused by infection with severe acute respiratory syndrome coronavirus 2. "Reassuringly, ORM1, IgA and AHSG are indicators of COVID-19 disease severity at the protein level, hence our results associated their differential glycosylation to severe COVID-19." (PMID 37474612, 2024). "The protein with the highest relevance in our model is Fetuin-A (AHSG), which is known to be strongly downregulated in severe COVID-19." (PMID 36812516, 2022). "Alpha-2 HS glycoprotein (AHSG) that modulates inflammation via attenuating macrophage activation and neutrophil degranulation and is significantly downregulated in severe COVID-19." (PMID 36143338, 2022). "Furthermore, by integrating protein-level and glycopeptide-level analyses, we identified glycan-specific regulation dependent on COVID-19 severity, most notably for IgA, alpha-2-HS-glycoprotein (AHSG) and alpha-1-acid glycoprotein (ORM1)." (PMID 37474612, 2024). "Similarly, another NeuroCOVID proteomic study on patient CSF showed AHSG (a glycoprotein) to be downregulated in COVID-19 patients, contrary to our upregulation of AHSG in the infected neurons." (PMID 38002279, 2023). "The alpha-2-HS-glycoprotein (AHSG) and the hepatocyte growth factor activator (HGFAC) were the only two proteins downregulated by COVID-19 across all severity groups; the rest of the proteins were differentially expressed in a severity-dependent manner." (PMID 38791465, 2024). "In our serum proteomics data, the abundances of AHSG, FETUB, HRG, and KNG1 are found to be highly correlated in each of the sampled COVID-19 patients and are consistently higher in the survivors." (PMID 34226277, 2021). "Moreover, the plasma proteins HRG, FETUB, KNG1, LCAT, AHSG, and FN1 increase over time in abundance in the Munich cohort, thus suggesting their regulation during COVID-19 disease development." (PMID 34226277, 2021). "Traditionally, CRP has been used as a systemic clinical marker of inflammation in COVID-19 and other diseases, although the SROC curves suggest that other acute phase proteins, such as ORM1, CRTAC1, SERPINA3, TF, and AHSG might perform better as biomarkers of inflammation." (PMID 37739942, 2023). "Most of the chosen markers change in abundance between healthy and COVID-19-infected individuals, and further follow their respective trend with increasing treatment escalation level, such as peptides derived from the acute-phase proteins CRP and AHSG, or the innate-immune-response protein PGLYRP2." (PMID 35702332, 2022).
ischemic stroke (15 papers, 2010 to 2025). A stroke disorder caused by obstruction of blood flow to the brain, due to thrombotic (local blood clot formation) or embolic (due to a blood clot or other material traveling from another site) event. "These associations may suggest an indirect role of AHSG in the pathogenesis of ischemic stroke through its influence upon stroke risk factors." (PMID 29245986, 2017). "AHSG, a plasma glycoprotein secreted predominantly by the liver, has been associated with atherosclerotic arterial calcifications, insulin resistance, cardiovascular disease, and particularly, ischemic stroke." (PMID 29245986, 2017).
Sepsis (13 papers, 2011 to 2026). Sepsis is defined as life-threatening organ dysfunction caused by a dysregulated host response to infection. "AHSG (Alpha-2-HS-glycoprotein) protein is mainly produced in the liver, and its level was decreased in sepsis patients." (PMID 35681439, 2022). "Expression of TMSB4X was found to be significantly increased in sepsis (p = 0.038) compared to HC and DNAJC13 and AHSG were found to decrease in sepsis compared to w/o sepsis." (PMID 35681439, 2022). "Alpha-2-HS-glycoprotein has been recognized for its neuroprotective capacity and its potent anti-inflammatory properties, particularly in the context of systemic inflammatory conditions, such as sepsis and autoimmune disorders." (PMID 40646861, 2025). "However, few downregulated proteins in sepsis patients compared to HC were AHSG, and PROS1, whereas compared to w/o sepsis, patients were AHSG, PROS1, DEFA1, SERPINA3, MPO, and MMRN1 (Azurophil granule, azurophil granule lumen and secretory granule lumen (GO:0042582, GO:0035578 and GO:0034774))." (PMID 35681439, 2022). "Proteomic analysis revealed that faulty functionality of neutrophils may be due to the autophagy proteins i.e., DNAJC13, AHSG, TMSB4X, PROS1 and SERPINA3, which can be used as therapeutic targets in decompensated cirrhosis patients with sepsis." (PMID 35681439, 2022). "We conclude that the faulty functionality of neutrophils may be due to the autophagy proteins, i.e., DNAJC13, AHSG, TMSB4X, PROS1, and SERPINA3, which can be used as therapeutic targets in decompensated cirrhosis patients with sepsis." (PMID 35681439, 2022).
Stroke (13 papers, 2010 to 2025). Sudden impairment of blood flow to a part of the brain due to occlusion or rupture of an artery to the brain. "Alpha-2-HS-glycoprotein, also known as fetuin-A (down-regulated; p < 0.0005), is a neuroprotective protein the function of which has been demonstrated in a rat stroke model and in early brain ischemic injury, whereby it attenuates the brain inflammatory response." (PMID 27082425, 2016). "Although FTL was more expressed than AHSG, TTR, and FGG using gene expression data for normal human tissues, it remains debatable whether iron itself and iron accumulation were beneficial or harmful after experimental stroke." (PMID 34168538, 2021).
kidney damage (12 papers, 2010 to 2025). "In many studies, the polymorphism of the gene encoding fetuin-A (AHSG)—the rs4917 polymorphism—also appears to be associated with kidney damage or disease." (PMID 41155157, 2025).
breast carcinoma (10 papers, 2011 to 2025). "AHSG is a serum glycoprotein involved in endocytosis, brain development, and the formation of bone tissue previously associated with resistance to neoadjuvant chemotherapy in patients with advanced breast cancer." (PMID 26504848, 2015). "Another protein identified in exosomes, alpha-2-HS-glycoprotein (AHSG), was found to promote breast cancer progression and was associated with the risk of colorectal carcinoma and non-small cell lung cancer (NSCLC)." (PMID 38200509, 2024). "In a previous study, anti-Alpha-2-HS-glycoprotein (AHSG) antibodies were detected in 33 of 36 patients with breast cancer (91.7%)." (PMID 33267867, 2020). "Difference expression of alpha-2-HS-glycoprotein exists in breast cancer, CRC, lung cancer, liver cancer, head and neck cancer." (PMID 24618180, 2014). "AHSG expression was upregulated in serum samples of stage IV obese breast cancer patients." (PMID 32709962, 2020). "Model 1 was built using three proteins previously identified as potential biomarkers of breast cancer in blood and/or tissue: Cofilin 1 (CFL1, LGGSAVISLEGKPL), Alpha-2-HS-glycoprotein (AHSG, HTFMGVVSLGSPSGEVSHPR), and Filamin A (FLNA, SPFSVAVSPSLDLSK)." (PMID 33267867, 2020).
gestational diabetes mellitus (9 papers, 2012 to 2025). "Moreover, an association between the rs4918 polymorphism in AHSG and the occurrence of gestational diabetes mellitus (GDM) has also been observed." (PMID 41155157, 2025).
Cirrhosis (7 papers, 2021 to 2025). A chronic disorder of the liver in which liver tissue becomes scarred and is partially replaced by regenerative nodules and fibrotic tissue resulting in loss of liver function. "The VC(cam)QDC(cam)PLLAPLNDTR glycopeptide of Alpha-2-HS-glycoprotein is a good example with higher contribution of tetra-antennary glycoforms in the cirrhosis groups while the bi-antennary and triantennary glycoforms remain the same." (PMID 34857845, 2021). "Alpha 2-HS glycoprotein (AHSG), a serum glycoprotein produced predominantly by hepatocytes, is an important biomarker of near-term mortality in patients with cirrhosis and HCC." (PMID 35935258, 2022).